MYD88 (MYD88 innate immune signal transduction adaptor)
Diseases named in the same sentence as MYD88 in open-access papers (continued):
Sharing a sentence is not in itself a finding about the gene and the disease.
Cognitive impairment (30 papers, 2011 to 2026). Abnormal cognition is characterized by deficits in thinking, reasoning, or remembering. "Following intracerebral hemorrhage, TLR4 is activated via the MyD88 signaling pathway causing brain oxidative injury and cognitive impairment." (PMID 36523959, 2022). "Taken together, these findings provide evidence that acupuncture attenuates cognitive impairment associated with inflammation through inhibition of the miR-93-mediated TLR4/MyD88/NF-κB signaling pathway in experimental VD." (PMID 32850002, 2020). "In mouse model of AD, MyD88 has been found to prevent memory and cognitive deficits while another study found MyD88 deficiency to improve AD-related pathology." (PMID 23843682, 2013). "Furthermore, transplantation of MyD88-deficient myeloid cells is more effective at ameliorating brain Aβ levels and cognitive deficits compared with MyD88-normal myeloid cells in an AD mouse model." (PMID 40028337, 2025). "The researchers proposed acupuncture attenuates cognitive impairment associated with inflammation through inhibition of the miR-93-mediated TLR4/MyD88/NF-κB signaling pathway in experimental VD, and acupuncture may be an underlying TLR4 inhibitor for the treatment of VD." (PMID 36204718, 2022). "Therefore, we hypothesise that cancer pain patients carrying the rs6853 SNP are at lower risk of developing cognitive dysfunction due to reduced MyD88 activity driving the neuroimmune signalling associated with cognitive impairment." (PMID 26332828, 2015). "This is distinct from previous studies which did not explore the connection between neuron necroptosis and microglial activation via TLR4/MyD88 in the context of PTX-induced cognitive impairment." (PMID 40322465, 2025). "This study reveals that hippocampal neuron necroptosis activates microglia through the TLR4/MyD88 signaling pathway in PTX-induced cognitive impairment, promoting M1 polarization and neuroinflammation." (PMID 40322465, 2025). "Targeting neuroinflammation with alogliptin, a dipeptidyl peptidase-4 inhibitor, has shown neuroprotective effects by targeting the TLR4/MYD88/NF-κB signaling cascade against lipopolysaccharide (LPS)-induced neuroinflammation and cognitive impairment in mice." (PMID 40801649, 2025). "Future studies should focus on in vivo models to confirm the role of TLR4/MyD88 in neuroinflammation and cognitive impairment and further explore its therapeutic potential." (PMID 40322465, 2025). "In this study, MYD88 levels were down-regulated by minocycline treatment that ameliorated cognitive impairment, possibly through its anti-inflammatory action." (PMID 35277123, 2022). "In summary, this study demonstrated that hippocampal neuron necroptosis activates microglia through the TLR4/MyD88 signaling pathway in PTX-induced cognitive impairment, promoting M1 polarization and neuroinflammation, while inhibiting necroptosis promotes M2 polarization and neuroprotection." (PMID 40322465, 2025). "Free heme induces cognitive impairment, and the underlying mechanism may involve neuronal apoptosis and microglial inflammation via the TLR4/MyD88/NF-κB signaling pathway." (PMID 38183122, 2024). "Consistently, studies have proven that regulating the TLR4/MyD88/NF-κB pathway in microglia might take part in neuroinflammation and cognitive impairment." (PMID 38183122, 2024). "LPS entering the brain then bind to Toll-like receptor 4 (TLR4) receptors on microglia, initiating the downstream NF-κB signaling pathway via MyD88, leading to the secretion of large amounts of pro-inflammatory cytokines, resulting in more intense neuroinflammation and cognitive impairment." (PMID 39101143, 2024). "We provided several lines of evidence supporting the hypothesis that free heme could induce neuroinflammation and cognitive deficits by microglial activation via the TLR4/MyD88/NF-κB signaling pathway." (PMID 38183122, 2024).
Cognitive impairment (continued). "It has been shown that neuronal apoptosis and microglia activation in hyperuricemia-mediated cognitive deficits mice are ameliorated by blocking the Myd88/NF-ĸB pathway to modulate the expression of the inflammatory factors IL-6 and the caspase family in mice serum." (PMID 38257230, 2024). "We observed that KXS upregulated AKT phosphorylation, suppressed GSK3β and CDK5 activation, and inhibited the TLR4/MyD88/NF-κB signaling pathway to attenuate Tau hyperphosphorylation and neuroinflammation, thus suppressing neuronal apoptosis and improving the cognitive impairment of aged SAMP8 mice." (PMID 35303280, 2022). "Treatment with EA may reduce the blood ammonia level, modulate inflammatory factors, ameliorate brain necrosis and apoptosis, and improve cognitive impairment through regulation of TLR4/MyD88/NF-κB and p38MAPK/STAT3 signaling pathways." (PMID 34630618, 2021). "Finally, we show that the TLR4/MyD88/NF-κB signaling pathway may be involved in free heme-induced neuroinflammation and cognitive deficits." (PMID 38183122, 2024). "Intraperitoneal injection of hemin induced cognitive impairment, increase of CD91 + cells, up-regulation of TNF-α and IL-1β, down-regulation of IL-6, activation of microglia, and activation of the TLR4/MyD88/NF-κB signaling pathway in rat brain." (PMID 38183122, 2024). "For example, TLR4/MyD88 signaling activation by S100A8 promotes neuroinflammation and contributes to tibial fracture surgery-induced cognitive disorders." (PMID 34530841, 2021).
hepatocellular carcinoma (30 papers, 2009 to 2025). A malignant tumor that arises from hepatocytes. "Therefore, we tested whether an in vitro system of hepatoma cells could demonstrate a similar association between MyD88 levels and SMAD4/hepcidin expression." (PMID 30234111, 2018). "For example, ectopic expression of MyD88 has been shown to enhance the invasion of hepatocellular carcinoma cells, whereas MyD88 inhibition has led to reduced lung metastasis and portal vein tumor thrombosis." (PMID 38347830, 2024). "Recent studies have reported that MyD88 is a novel downstream substrate of CacyBP in hepatocellular carcinoma." (PMID 38785969, 2024). "HBX can promote the expression of MyD88 at the transcriptional level in both liver and hepatoma cells." (PMID 35251017, 2022). "Enhanced Myd88 expression has been found in various parenchymal tumors especially in hepatocellular carcinoma with little mechanism of its upregulation known." (PMID 29022910, 2017). "MyD88, a pivotal signaling molecule, has garnered attention for its dysregulated expression in various cancer types, including colorectal cancer, ovarian cancer, hepatocellular carcinoma, and pancreatic cancer, highlighting its role in tumor progression." (PMID 38347830, 2024). "In the progression of hepatocellular carcinoma, the activation of Myd88 signaling could promote the proliferation and migration of hepatitis B virus-infected LX‐2 cells, and inhibit apoptosis." (PMID 37953776, 2023). "Specifically, the overexpression of HBx in hepatic and hepatoma cell lines activates TLR4 downstream signaling components such as myeloid differentiation primary response 88 (MyD88), IRAK1, and nuclear factor-kappaB (NF-κB), contributing to the secretion of IL-6, a major pro-inflammatory cytokine." (PMID 36298831, 2022). "Since interleukin-1 receptor and TLR4 signaling triggers MYD88 innate immune signal transduction adaptor (MyD88) activation cascade in monocytes, the effect of levantinib could be not only on hepatoma cells, but also on monocytes." (PMID 32397371, 2020). "APs may modulate immunity by activating the toll-like receptor 4 (TLR4)–mediated myeloid differentiation primary response 88 (MyD88)–dependent signaling pathway and induce apoptosis in human hepatocellular carcinoma cells by decreasing the expression of Notch1." (PMID 38466979, 2024). "Recent studies have further highlighted MYD88's pivotal role in intrinsic immunity and its regulatory influence on the tumor microenvironment (TME) in hepatocellular carcinoma (HCC)." (PMID 40196847, 2025). "We also show that overexpression of SMAD6 and SMURF1 in hepatoma cells inhibited HAMP-Luc activity, while endogenous MyD88 protein expression diminished." (PMID 30234111, 2018). "We show that MyD88 overexpression in Huh7 hepatoma cells increases endogenous SMAD4 protein levels, while conversely, suppression of MyD88 results in lowering SMAD4 levels." (PMID 30234111, 2018). "Downstream of TLR4 and MyD88, activated NF-κB can bind the SAA3 promoter and has been shown to regulate SAA3 transcription in hepatoma-derived cell lines and mouse adipocytes." (PMID 19513118, 2009). "In addition, a study showed that Myd88 signaling in myofibroblasts increased the secretion of CCL20, which promoted aerobic glycolysis of hepatocellular carcinoma cells and accelerated tumor cell growth." (PMID 37953776, 2023). "In addition to the PRR agonists, overexpression of PRR-related adaptors or RIG-I adaptors such as MyD88, MAVS, and TRIF can significantly control HBV replication in human hepatoma cells." (PMID 36298831, 2022).
myocardial infarction (29 papers, 2011 to 2025). Gross necrosis of the myocardium, as a result of interruption of the blood supply to the area, as in coronary thrombosis. "In a mouse model of I/R injury, Feng and colleagues found that compared to WT mice, mice deficient in MyD88 had markedly reduced myocardial infarction and significantly improved LV function between day 1 and day 7 after transient ischemia as measured by transthoracic echocardiography." (PMID 21977329, 2011). "Myocardial infarction is closely associated with hypoxia-related genes such as SELP, CXCL2, MyD88, and S100a8 and genes related to Atf3, PTGS2, Cxcl1, and Socs3 ferroptosis." (PMID 37181809, 2023). "MyD88 mediates the TLR4/NF-κB inflammatory pathway to prevent isoproterenol- (ISO-) induced AMI, and inhibiting MyD88 expression prevents pathological left ventricular remodeling and alleviates myocardial infarction injury." (PMID 37181809, 2023). "For instance, Nicorandil suppresses TLR4/MyD88/NF-κB/NLRP3 axis to alleviate pyroptosis in rats with myocardial infarction." (PMID 34595225, 2021). "TLR4/MyD88‐NF‐κB pathway is involved in the process of DCs maturation and inflammatory response in the development and progression of myocardial infarction with concurrent hyperlipidemia." (PMID 32073735, 2020). "SOD1 overexpression, RELA blockade, and diminished MyD88-mediated inflammation can enhance functional and metabolic recovery and greatly decreased myocardial infarction, while ADIPOR2 is required for revascularization." (PMID 32565767, 2020). "This study was intended to discover the prospective cardioprotective actions of β-caryophyllene, a natural sesquiterpene, to ameliorate isoproterenol (ISO)-induced myocardial infarction through HSP-60/TLR/MyD88/NFκB pathway." (PMID 31109132, 2019). "We also tried to explore endogenous TLR ligands and HSP-60/TLR/MyD88/NFκB signaling pathway to resolve their role in myocardial infarction through NFκB." (PMID 31109132, 2019). "Employing genetically modified mouse models or local transgene expression of dominant negative MyD88 (dn-MyD88), investigators demonstrate that MyD88 signaling participates in I/R-induced myocardial inflammation and myocardial infarction." (PMID 21977329, 2011). "Increasing evidence suggests that inhibition of the TLR4/MyD88/NF-κB/NLRP3 inflammasome pathway may reduce myocardial infarction-induced pyroptosis." (PMID 34595225, 2021). "In the current study, myocardial and serum levels of TNF- α in rats fed with high-fat diets and isoproterenol-induced myocardial infarction animals were evaluated to clarify the correlation between TLR4/MyD88 protein expressions in myocardium and production of proinflammatory cytokines." (PMID 32211137, 2020). "TLR4, TLR2, MyD88, and TRIF protein levels via western blot in the heart tissue were measured following ISO-induced myocardial infarction to determine whether β-caryophyllene could suppress TLR activity through MyD88 down-regulation." (PMID 31109132, 2019). "Moreover, another study showed that nicorandil could alleviate pyroptosis in rats with myocardial infarction by influencing the TLR4/MYD88/NF-κB/NLRP3 pathway." (PMID 38095638, 2023). "β-Caryophyllene at doses of 100 and 200 mg/kg lessened post- myocardial infarction TLR activity measured as the protein content of TLR2 (A), TLR4 (B), MyD88 (C), and TRIF (D) in the heart tissue (p < 0.05)." (PMID 31109132, 2019). "Our results showed that ISO-induced myocardial infarction is accompanied by significant escalations in levels of the TLR2, TLR4, MyD88, and TRIF, enhancing subsequent inflammatory mediator signaling." (PMID 31109132, 2019). "Myocardial infarct sizes, histological scores, levels of circulating and myocardial IL-6 and TNF-α, the expression of HMGB1, TLR4, MyD88 and NF-κB, and the degradation of IκB were significantly increased in the I/R group compared with the sham group (P<0.01)." (PMID 28222157, 2017).
myocardial infarction (continued). "Recently we demonstrated that TLR4 and MyD88 were increased in brainstem of myocardial infarction (MI)-induced heart failure, and that intracerebroventricular (ICV) injection of angiotensin II type 1 receptor blocker prevented LV remodeling with sympathoinhibiton and reduction of TLR4 in brainstem." (PMID 23874864, 2013). "As a result of weak GMA intervention, the expression of TLR4, TRAF6, NF-κB, and TNF-α was significantly decreased, the expression of MyD88 and MCP-1 was increased, the inflammatory response was blunted, the area of myocardial infarction was reduced, and cardiac function was improved." (PMID 38197985, 2024). "It suppresses p38 MAPK signaling pathway, and reduces arrhythmogenesis following myocardial infarction, and enhances cardiac function.It inhibits the expression of TLR4, MyD88, GM-CSF, IL-1β, TNF-α, and COX-2, and attenuates LPS-mediated TLR4-NF-κB pathway activation." (PMID 33868227, 2021). "HSPB1 knockout mice subjected to myocardial infarction (MI) exhibited enhanced and prolonged leukocyte infiltration, enhanced inflammatory cytokine expression, and enhanced toll-like receptor 4 (TLR4)/myeloid differentiation factor 88 (MyD88)/NF-κB activation in their heart tissue." (PMID 37252119, 2023).
Insulin resistance (28 papers, 2010 to 2024). Increased resistance towards insulin, that is, diminished effectiveness of insulin in reducing blood glucose levels. "Female mice with skeletal muscle-specific MyD88 deficiency are protected from inactivity-induced adiposity and insulin resistance." (PMID 33376487, 2020). "In this context, it is important to note that deficiency of MyD88 has varied effects on insulin resistance depending on cell type in which it is deleted." (PMID 26317499, 2015). "Furthermore, hepatocyte-specific deletion of MyD88 is a predisposing factor for glucose intolerance, inflammation, and hepatic insulin resistance (IR)." (PMID 38291436, 2024). "In contrast, global MyD88-deficient mice demonstrate worse insulin resistance upon HFD-feeding." (PMID 26317499, 2015). "Acute exposure to LPS can cause transient hypoglycemia and insulin resistance by inhibiting hepatic glucose production through the TLR4, MyD88, and NFκB pathways." (PMID 35622768, 2022). "There is therefore a conflict regarding the activity of the TLR4/MyD88 axis in diet-induced obesity and insulin resistance, which remains to be elucidated in future studies." (PMID 23964268, 2013). "As TNF-αis involved in the development of insulin resistance and that MyD88 is involved in activating inflammatory signals, we measured liver TNF-αlevels in these mice." (PMID 20824098, 2010). "Together, these results point to the fact that macrophages are the first immune cells to infiltrate AT inducing ECM remodeling, which may be instrumental in insulin resistance development through the TLR2/Myd88/NFκB pathway." (PMID 37445827, 2023). "Mice with hepatocyte-specific MyD88 deficiency are prone to develop glucose intolerance, inflammation, and hepatic insulin resistance regardless of bodyweight." (PMID 33376487, 2020). "Furthermore, brain specific deletion of MyD88 (myeloid differentiation factor), a downstream mediator of TLR4 signaling, in mice also prevent HFD-induced obesity and associated leptin and insulin resistance." (PMID 30906281, 2019). "Importantly, IEC MyD88-KO HFD mice exhibited an improved oral glucose tolerance compared with WT HFD mice, an effect that was associated with a decrease in insulin resistance index." (PMID 25476696, 2014). "Thus, along with the involvement of MyD88, a molecule that is essential for the generation of pro-inflammatory cytokines, these results strongly implicate neuroinflammation as a mediator of palmitate-induced insulin resistance." (PMID 34831343, 2021). "This ultimately leads to insulin resistance especially in the continuous or chronic and persistent stimulation of the TLR signaling pathway through expression of TLR4, MyD88 and NFκB." (PMID 31738794, 2019). "For example, mice that have a specific deletion of MyD88 in neuronal cells are protected from HFD-induced weight gain and insulin resistance." (PMID 26317499, 2015). "Knockdown of protein kinase C theta in the ARC or toll-like receptor 4 (TLR4)-adaptor molecule, MyD88, in the CNS prevented HFD- or ICV palmitate-induced weight gain and insulin resistance, highlighting some of the mechanisms of palmitate-induced central insulin resistance." (PMID 34831343, 2021). "Accordingly, recent studies reported that genetic disruption of key inflammatory pathways in the hypothalamus, such as TLR4/MyD88 or IKKb/NF-kB pathways, is protective against the metabolic complications induced by HFD including hypothalamic insulin resistance." (PMID 30906281, 2019). "Knockdown of myeloid differentiation primary response gene 88 (MYD88), an adaptor protein for TLR4, improved the insulin resistance in LKO mice, and overexpression of PRSS8 in the liver did not decrease blood glucose levels during the GTT and PTT in systemic TLR4 KO mice." (PMID 24614850, 2014).
Insulin resistance (continued). "Next, myeloid differentiation primary response protein 88 (MYD88), the primary mediator of TLR and IL1 receptor signaling, has been investigated to clarify whether this is also involved in the FFA-induced insulin resistance." (PMID 23964268, 2013).